TNF (tumor necrosis factor)
Diseases named in the same sentence as TNF in open-access papers (continued):
Sharing a sentence is not in itself a finding about the gene and the disease.
atherosclerosis (continued). "Significant changes in the activity of the genes that code for TNF-α and CX3CL1 have been reported at the site of atherosclerosis." (PMID 25959742, 2015). "In accordance with the nature of atherosclerosis as a chronic inflammatory disease, the levels of plasma IFN-γ, TNF-α and IL-6, three major inflammatory biomarkers, were significantly increased in AS patients compared with those in healthy subjects." (PMID 26071079, 2015). "Low levels of vitamin D increase TNF-α levels and decrease IL-10 levels because TNF-α worsens intimal atherosclerosis and vascular calcification and IL-10 has antiatherogenic properties." (PMID 26618538, 2015). "In recent years, it has emerged that TNF signaling plays a role in CAD pathogenesis, the development of atherosclerosis, heart failure, and the progression of myocardial disease." (PMID 26636103, 2015). "Systemic increases in these inflammatory molecules, together with tumor necrosis factor and CRP, occur during the atherosclerosis process." (PMID 25433580, 2015). "Atherosclerosis involves the release of inflammatory cytokines, such as interleukin 1-β (IL1-β) and tumor necrosis factor-α (TNFα) which participate in pro-inflammatory signaling." (PMID 24755612, 2014). "Atherosclerosis induced by a high-fat diet was characterized by a gradual increase in the levels of the inflammatory cytokines IL-1β, IL-6, MCP-1 and TNF-α compared with the control group." (PMID 25120600, 2014). "As a key regulator of atherosclerosis, NF-κB regulates the expressions of various inflammatory factors, including VCAM-1, MCP-1, IL-6 and TNF-α, which in turn accelerate the progress of chronic inflammation." (PMID 24621517, 2014). "Most adipokines, such as tumor necrosis factor (TNF)-α, interleukin (IL)-6, visfatin and leptin are well-known pro-inflammatory cytokines that accelerate atherosclerosis in experimental model, and contribute to the presence of ACS." (PMID 25367628, 2014). "However, so far, studies were not able to conclude whether TNF-α is a causative factor of atherosclerosis." (PMID 24741576, 2014). "It is able to reduce serum levels of TNFα and IL6 and plays a protective role against atherosclerosis." (PMID 25136143, 2014). "Previous studies from our lab as well as others have shown that several members of the tumor necrosis factor (TNF) superfamily, including CD40-CD40L, LIGHT, and OX40-OX40L, are involved in atherosclerosis development." (PMID 24520398, 2014). "Progranulin also significantly reduced the expression of tumor necrosis factor receptor-α (TNF-α) and monocyte chemo-attractant protein-1 (MCP-1), the crucial inflammatory molecules known to aggravate atherosclerosis." (PMID 24098801, 2013). "Accumulating evidence suggests that the induction of VCAM-1 or ICAM-1 by TNF-α in endothelium is mediated by the activation of MAPK and transcription factors such as NF-κB, leading to the pathogenesis of atherosclerosis." (PMID 23401716, 2013). "The pro-inflammatory cytokine, tumor necrosis factor (TNF)-α, is a prototype “activation agonist” that modulates leukocyte adhesion and transmigration in vascular inflammatory diseases including atherosclerosis." (PMID 22754320, 2012). "Tumor necrosis factor (TNF, also called TNF-α), is a major pro-inflammatory cytokine involved in the pathogenesis of atherosclerosis and various other inflammatory diseases." (PMID 23285008, 2012). "Elevated concentrations of proinflammatory cytokines such as TNFα, and CRP play a significant role in the genesis of atherosclerosis and in plaque instability." (PMID 22745783, 2012). "Our data from this shear stress flow model suggest that mast cell–derived TNF-α and IL6 contribute to leukocyte adhesion during the pathogenesis of atherosclerosis or other vascular diseases." (PMID 21264293, 2011).
atherosclerosis (continued). "Proinflammatory cytokines, such as interleukin (IL)-1β, IL-6 and tumor necrosis factor (TNF)-α and the acute phase reactant C-reactive protein (CRP) have important effects in inflammation and atherosclerosis." (PMID 21695270, 2011). "Several studies have shown that pro-inflammatory cytokines, such as tumor necrosis factor (TNF)-α, interleukin (IL)-1β, and IL-6, play an important role in the development of atherosclerosis." (PMID 20946675, 2010). "Concomitant with a reduced NF-κB activation in the aortic arches, as assessed by IκBα expression, we also found reduced expression of TNF, IL-6, MCP-1 and RANTES, all proven to be important in atherosclerosis." (PMID 19582157, 2009). "The most pronounced increase in medial TNF-α expression occurred at 16 weeks of age, at the same time as the highest TNF-α mRNA levels was detected and as a more wide-spread atherosclerosis began to develop." (PMID 23675033, 2007). "In addition, PFKFB3 promotes ECs inflammation via tumor necrosis factor-α(TNF-α), which promotes the development of atherosclerosis." (PMID 41149255, 2025). "miR-155 influences TNF-α mRNA stability by inhibiting calcium regulated heat stable protein 1 (CARHSP1), thereby modulating the inflammatory response and protecting vessels in atherosclerosis." (PMID 40051627, 2025). "In atherosclerotic plaques, GITR’s staining pattern overlaps with that of MMP-9 and TNF-α, suggesting GITR-mediated macrophage activation may promote atherosclerosis development and plaque instability." (PMID 41268556, 2025). "In addition, the KEGG pathway analysis HXF acting on PF mainly involves cancer pathway, lipid and atherosclerosis, PI3K-AKT signaling pathway”, chemical carcinogenesis-receptor activation, TNF signaling pathway and other signaling pathways." (PMID 40404681, 2025). "Unlike IL-6, TNF-α has not yet been shown tohave a dual nature of action in atherosclerosis: that is, it exhibits exclusivelypro-inflammatory effects." (PMID 40160593, 2025). "Studies have also demonstrated that high concentrations of proinflammatory molecules, including tumor necrosis factor-alpha (TNF-α) and interleukin-6 (IL-6), contribute to the accelerated development of atherosclerosis and cardiovascular events in patients with RA and SLE." (PMID 40046046, 2025). "KEGG enrichment analysis revealed that these targets are closely related to lipid and atherosclerosis, the PI3K‐Akt, MAPK, IL‐17, and the TNF signaling pathways, Alzheimer's disease, apoptosis, pathways of neurodegeneration involving multiple diseases, and the neurotrophin signaling pathway." (PMID 40994138, 2025). "HOXA5 safeguards against atherosclerosis via peroxisome proliferator-activated receptor gamma (PPARγ), whereas HOXB9 exacerbates inflammation through bone morphogenetic protein 4-tumor necrosis factor (BMP4-TNF)." (PMID 41181801, 2025). "In the context of atherosclerosis, IF can reduce LDL-C and attenuate systemic inflammation, such as the suppression of IL-6 and TNFα, which may exert anti-atherogenic effects." (PMID 40861271, 2025). "Previous studies have shown that low muscle density is associated with increased intramuscular fat accumulation, which promotes inflammation through upregulation of cytokines such as interleukin-6 (IL-6) and tumor necrosis factor-α (TNF-α), thereby accelerating atherosclerosis." (PMID 41299285, 2025). "Similarly, TNF-α and IFN-γ, central mediators of proinflammatory responses in atherosclerosis, were upregulated in the aortic arch of MerTKflox/floxTie2Cre mice compared to the control MerTKflox/flox mice." (PMID 40953531, 2025). "Additionally, vitamin B6 modulates immune responses by reducing pro-inflammatory cytokines (e.g., IL-6, TNF-α), which are elevated in CKD and contribute to atherosclerosis." (PMID 40357033, 2025). "Pro-inflammatory cytokines (IL-6, TNF-α, CRP) → endothelial dysfunction, atherosclerosis." (PMID 40566026, 2025).
atherosclerosis (continued). "KEGG enrichment analysis showed that drug targets were associated with pathways in cancer, neuroactive ligand-receptor interaction, lipid and atherosclerosis, AGE-RAGE signaling pathway in diabetic, cellular senescence, MAPK signaling pathway, TNF signaling pathway, and HIF-1 signaling pathway." (PMID 40065477, 2025). "The KEGG enrichment analysis showed that DEGs were significantly associated with pathways such as longevity regulation, lipid metabolism and atherosclerosis, pluripotency of stem cells, apoptosis, VEGF, HIF-1, TNF, MAPK, Wnt, mTOR, and Hippo signaling pathways." (PMID 40563849, 2025). "Pro-inflammatory cytokines, including TNF-α, COX-2, and IL-6, recruit monocytes to the vessel wall, augment ox-LDL uptake, and enhance SR expression, thereby accelerating foam cell formation and atherosclerosis." (PMID 40475061, 2025). "Similarly, gene set enrichment analysis (GSEA) showed that MICU1 depletion upregulated TNF signaling, TLR signaling, and atherosclerosis-related pathways." (PMID 40166941, 2025). "Furthermore, the MAPK pathway engages in crosstalk with other critical signaling pathways, such as TNF, PI3K-Akt, and NF-κB, collectively orchestrating inflammatory responses and vascular remodeling in atherosclerosis." (PMID 40141309, 2025). "Furthermore, fraxin downregulated IL-6 and TNF-α expression and lowered the gene and protein levels of FAT/CD36, controlling key targets in signaling pathways related to lipid metabolism and atherosclerosis." (PMID 41458968, 2025). "Similarly, tumor necrosis factor-α (TNF-α), a regulator of inflammation and immune responses, when overproduced in CHD patients, can heighten the inflammation and expedite atherosclerosis progression." (PMID 40417004, 2025). "As inflammation contributes to the progression of atherosclerosis, TCZ treatment may be beneficial in protecting patients with RA from cardiovascular events, similar to tumor necrosis factor-alpha (TNF-α) blockers." (PMID 39897309, 2025). "This research reveals that KMUP-1 co- and posttreatment could inhibit atherosclerotic plaque formation and atherosclerosis lesions by suppressing inflammation in HFD-fed mice (i.e., elevation of IL-1β and TNF-α)." (PMID 41194853, 2025). "The KEGG enrichment results revealed that the key targets were mainly enriched in lipid metabolism, atherosclerosis, the AGE-RAGE signaling pathway in diabetic complications, the TNF signaling pathway, the VEGF signaling pathway, apoptosis, and other signaling pathways." (PMID 40832612, 2025). "The experiments performed in vitro demonstrated that TNFα stimulated the phagocytosis of LDL by human umbilical vein endothelial cells (HUVECs) and promoted the retention of LDL beneath the vascular wall, thus accelerating atherosclerosis progression." (PMID 40861271, 2025). "We found that GYS mainly interfered with mastitis through the PI3K-Akt signal pathway, the MAPK pathway, the TNF signaling, the AGE-RAGE pathway, and the fluid-shear stress and atherosclerosis pathways, which are closely related to the reported pathology of mastitis." (PMID 38630770, 2024). "KEGG pathway analysis showed that there was an enrichment in the various pathways, including lipid and atherosclerosis, chemokine signaling pathway, endoplasmic reticulum protein processing, NOD-like receptor signaling pathway, TNF signaling pathway, and IL-17 pathway." (PMID 39502647, 2024). "Type-1 cytokines (TNF-α, IFN-γ) are known to aggravate atherosclerosis in experimental models." (PMID 38638438, 2024). "Cluster analysis emphasized IL6, TNF, AKT1, and VEGFA’s roles in atherosclerosis and inflammation." (PMID 38496269, 2024).
atherosclerosis (continued). "Therefore, this study aimed to gain insight into the relationship between plasma concentrations of TNF, VEGF, IL-6, and radiological parameters of atherosclerosis progression in patients with early-onset coronary artery disease (CAD)." (PMID 38541966, 2024). "Furthermore, inflammation isdescribed as a key mechanism in the development of atherosclerosis, withC-reactive protein (CRP), interleukins, tumor necrosis factor-alpha (TNF-α), andtransforming growth factor-beta (TGF-β1) identified as risk factors." (PMID 39076488, 2024). "Specifically, the cutoff values for TNF-alpha and hsCRP indicated high sensitivity and specificity, suggesting that elevated levels of these markers can reliably predict a higher IMT, a surrogate marker for atherosclerosis." (PMID 39518658, 2024). "Cadmium accumulation also increases multiple important pro-inflammatory cytokines such as interleukin (IL)-6, IL-8, IL-1β, and tumor necrosis factor α (TNF-α), which may play a critical role in atherosclerosis." (PMID 39415790, 2024). "The median (IQR) of TNF-α in psoriasis vulgaris patients without and with atherosclerosis was 1.10 (0.13–4.60) and 0.54 (0.13–3.41) pg/mL, respectively (p < 0.05)." (PMID 39104857, 2024). "For flaxseed oil exhibited anti-atherosclerosis activity on high-fat diet-induced ApoE−/− mice, alloLCA and isoLCA were positively correlated with LPS in plasma, and CDCA and HDCA were positively correlated with TNF-α in aorta." (PMID 39403395, 2024). "QED might interfere and treat RA through lipid and atherosclerosis, cancer pathways, PI3K-Akt, AGE-RAGE, IL-17, TNF, as well as HIF-1 signaling pathways." (PMID 40190499, 2024). "In this study, hsa-miR-203a-3p was predicted to regulate TNF and CCR5, suggesting that miRNAs might affect the progression of gout as well as atherosclerosis by modulating the expression of these key inflammatory and immune-related genes." (PMID 39677038, 2024). "Similarly, exosomes from dendritic cells, through TNF-α and NF-kB signaling, promote adhesion molecules like VCAM-1, ICAM-1, and E-selectin thereby heightening inflammation and atherosclerosis." (PMID 39766337, 2024). "The levels of circulating pro-inflammatory cytokines, such as interleukin-1 beta (IL-1β), interleukin-6 (IL-6), and tumor necrosis factor-alpha (TNF-α), which are elevated in T2DM patients, underscore the relationship between T2DM and inflammation in the pathogenesis of atherosclerosis." (PMID 39125322, 2024). "The median TNF-α level in healthy controls was significantly lower than in psoriasis vulgaris patients without atherosclerosis (p < 0.05) but not in those with atherosclerosis (p > 0.05)." (PMID 39104857, 2024). "Moreover, GSEA results suggested that DEN + HFHC induction accelerated lipid and atherosclerosis, lipid storage, NAFLD, and TNF signaling pathway." (PMID 38724499, 2024). "Macrophages are prominent inflammatory cells in atherosclerotic lesions and produce a series of inflammatory factors, such as interleukin (IL)-1β, tumor necrosis factor (TNF)-α, IL-6, IL-8, monocyte chemoattractant protein-1 (MCP-1), triggering inflammation-induced atherosclerosis." (PMID 38957396, 2024). "Cytokines and growth factors initiate the JAK/STAT pathway, and the downstream of JAK/STAT includes diverse genes involved in proliferation and apoptosis in atherosclerosis, such as IL-6, interferon (IFN)-γ, TNF-α and the suppressor of cytokine signaling (SOCS)." (PMID 39598338, 2024). "Blood TNFα levels were higher in patients with atherosclerosis compared to those without and higher in ischemic heart failure patients compared to coronary artery disease patients." (PMID 38256155, 2024). "We next tested whether combined treatment with anti‐TNFα, anti‐CXCL2, and anti‐CCL2 would reduce the ability of aged fat transplants to enhance atherosclerosis." (PMID 36683460, 2023).
atherosclerosis (continued). "Inflammatory modulators/biomarkers, such as IL-1α, IL-1β, IL-6, IL-12, IL-15, IL-18, and tumor necrosis factor α, or alternative anti-inflammatory cytokine IL-10, and adhesion molecules (ICAM-1, VCAM-1), involved in atherosclerosis progression have been shown to predict cardiovascular diseases." (PMID 37374202, 2023). "Furthermore, fluid shear stress and atherosclerosis, the HIF-1 signaling pathway, and the TNF signaling pathway are highly participated in angiogenesis, pro-inflammatory factor secretion, and vascular tone regulation." (PMID 37076581, 2023). "Additionally, new biomarkers of atherosclerosis (IL-6, MPO, TNF-alpha) will be measured every 6 months." (PMID 37590267, 2023). "Through analysis of protein functional enrichment, it was found that AR may act on IL-6, TNF-α, ICAM-1, VCAM-1, and MCP-1 and play anti-atherosclerosis and neuroprotective roles." (PMID 37361203, 2023). "Clinical periodontal parameters, TNF-α and IL-8 in GCF and IL-17A, hs-CRP, and LDL in serum, had more significant predictive roles in developing subclinical atherosclerosis (IMT ≥ 0.75 mm) in comparison with other cytokines, fibrinogen, and other lipid status parameters." (PMID 36983201, 2023). "However, despite their crucial roles, the overproduction of pro-inflammatory cytokines, i.e., IL-6, IL-1b, and tumor necrosis factor alpha (TNF-α), induces severe adult diseases, such as allergy, arthritis, atherosclerosis, and cancer." (PMID 37891941, 2023). "In addition, increasing evidence demonstrated that inflammatory factors like tumor necrosis factor-α, interleukin-6, and interleukin-8 can also be released from PAT, which is involved in the pathogenesis of atherosclerosis." (PMID 37964956, 2023). "Furthermore, it inhibits NF-κB phosphorylation and the secretion of proinflammatory factors such as TNF-α and MCP-1 induced by LPS during atherosclerosis." (PMID 38003338, 2023). "In atherosclerosis and endothelial dysfunction, activation of LOX-1 stimulates the NF-κB signaling pathway to promote the expression of proinflammatory cytokines, such as IL-1b, TNF-α, MCP1, IL-8, and IL-6." (PMID 36982155, 2023). "Serum proteomics research results show that AR may act on IL-6, TNF-α, VCAM-1, MCP-1, and ICAM-1, and play anti-atherosclerosis and neuroprotective roles." (PMID 37361203, 2023). "IL-17E expression in patients with CAD correlates with TNFα, IL-6 levels, and Gensini score in atherosclerosis, with a zero score indicating no atherosclerosis." (PMID 36197585, 2023). "Factors involved in the Th1 reaction, including tumour necrosis factor-α (TNF-α), recombinant human interferon-γ (IFN-γ), interleukin (IL)-12, and IL-18, have been proven to promote atherosclerosis through leukocyte recruitment, EC injury, and oxidative stress." (PMID 38143759, 2023). "As atherosclerosis is known to be induced by vascular inflammation, we studied the effect of GV1001 on vascular inflammation in WT mice by determining the expression levels of pro-inflammatory cytokines, such as IL-1β, TNF-α, and IL-6." (PMID 37628753, 2023). "TNF-α blocking therapy had no significant overall effect on the atherosclerosis index in RA patients." (PMID 37325667, 2023). "During inflammation, TNF‐α increases human antigen R (HuR) translocation and its binding to 3′UTR of ICAM‐1 mRNA which boosts the adhesion of white blood and aortic endothelial cells and eventually inflammation and atherosclerosis." (PMID 37457142, 2023). "In previous studies, Nur77 expression could be induced in macrophages by several stimuli related to development of atherosclerosis such as oxidized low-density lipoprotein (ox-LDL), lipopolysaccharide (LPS), and tumor necrosis factor-α (TNF-α)." (PMID 35464766, 2022).